MUC5B (mucin 5B, oligomeric mucus/gel-forming)
Description:
Gel-forming mucin that is thought to contribute to the lubricating and viscoelastic properties of whole saliva and cervical mucus.
Synonyms: MUC-5B; MUC5; MG1; MUC9
Tractability: Antibody: its Gene Ontology location is reachable by antibodies, with high confidence; UniProt places it where antibodies can reach, with medium confidence; UniProt predicts a signal peptide or a membrane-spanning region.
Gene: Protein-coding gene on chromosome 11 (1,223,066 to 1,262,172, forward strand). Ensembl gene ENSG00000117983.
Subcellular location: Secreted
Subcellular location (Human Protein Atlas): Vesicles; Predicted to be secreted
Pathways (Reactome):
Disease: Defective C1GALT1C1 causes TNPS; Defective GALNT12 causes CRCS1; Defective GALNT3 causes HFTC
Metabolism of proteins: O-linked glycosylation of mucins; Termination of O-glycan biosynthesis
Immune System: Dectin-2 family
Gene Ontology:
Molecular function: protein binding; extracellular matrix structural constituent
Biological process: negative regulation of single-species biofilm formation in or on host organism
Cellular component: extracellular exosome; extracellular region; extracellular matrix; Golgi lumen; plasma membrane
Genetic constraint (gnomAD): Loss-of-function variants: 108 observed, 316.73 expected, observed/expected ratio (o/e) 0.34, 90% interval 0.29 to 0.4. The upper end of that interval is the gene's LOEUF score, 0.4, which puts it in group 1 of 6, group 1 being the genes least tolerant of losing a copy. Missense variants: 7,075 observed, 7,118.3 expected, observed/expected ratio (o/e) 0.99, 90% interval 0.97 to 1.01. Synonymous variants: 3,464 observed, 3,070.3 expected, observed/expected ratio (o/e) 1.13, 90% interval 1.1 to 1.16.
Homologues: Orthologues: macaque MUC5B (65% identical), mouse Muc5b (36% identical), rat Muc5b (36% identical), zebrafish muc5.1 (26% identical), zebrafish muc5.2 (24% identical), zebrafish muc5.3 (23% identical). Paralogues in human: MUC5AC (31% identical), MUC19 (12% identical), MUC6 (12% identical), MUC2 (12% identical), VWF (11% identical), OTOG (10% identical), OTOGL (10% identical), FCGBP (8% identical), TECTA (7% identical), ZAN (6% identical), KCP (6% identical), CRIM1 (4% identical), and 7 more.
Diseases named in the same sentence as MUC5B in open-access papers:
MUC5B is named in the same sentence as 166 diseases in open-access papers, as found by Europe PMC text mining. Sharing a sentence is not in itself a finding about the gene and the disease. The quoted sentences say what the papers report.
pulmonary fibrosis (134 papers, 2012 to 2026). Chronic progressive interstitial lung disorder characterized by the replacement of the lung tissue by connective tissue, leading to progressive dyspnea, respiratory failure, or right heart failure. "We present a 47-year-old Asian male with Hermansky-Pudlak syndrome-associated pulmonary fibrosis (HPS-PF), a congenital right-sided aortic arch, and a MUC5B mutation-an exceptionally rare case of multifactorial pulmonary fibrosis complicated by lung cancer." (PMID 41953037, 2026). "It is estimated that MUC5B polymorphism (the presence of T minor allele) accounts for 30–35% risk of developing lung fibrosis and is the strongest single risk factor for developing IPF." (PMID 40076835, 2025). "The gain-of-function MUC5B promoter variant is the dominant risk factor for the development of idiopathic pulmonary fibrosis (IPF)." (PMID 40526433, 2025). "The largest known genetic-predisposing variant is the MUC5B promoter variant rs35705950, with an estimated six-fold excess risk of developing idiopathic pulmonary fibrosis (IPF) in heterozygotes and twenty-fold excess risk in homozygotes." (PMID 41465275, 2025). "Taken together, these findings suggest an age-related association between the MUC5B rs35705950 variant and the prevalence of pulmonary fibrosis." (PMID 40999395, 2025). "Multiple genome-wide association studies have confirmed that the T allele mutation at the rs35705950 site in the promoter region of the MUC5B gene increases the risk of idiopathic pulmonary fibrosis (IPF) and shortens overall survival." (PMID 40351459, 2025). "The mechanism by which the MUC5B promoter variant drives lung fibrosis is an active area of research." (PMID 40526433, 2025). "Four SNPs were associated with pulmonary fibrosis in RA: beyond the well-known MUC5B polymorphism rs35705950 and the TERT polymorphisms rs2736100, TOLLIP (rs111521887) and FAM13A (rs2609255) were also associated with a higher risk of ILD." (PMID 40066169, 2025). "Key genetic contributors include telomere maintenance genes, surfactant protein genes, and the MUC5B promoter variant rs35705950, which is the strongest known genetic risk factor for idiopathic pulmonary fibrosis." (PMID 41465275, 2025). "In conclusion, our findings suggest that the MUC5B promoter variant leads to protein changes in alveolar and airway epithelium that appear to be associated with initiation and progression of lung fibrosis." (PMID 40526433, 2025). "The MUC5B (rs35705950) promoter polymorphism has been reported with the presence of the minor T allele as a genetic risk factor for pulmonary fibrosis and has been validated to increase the risk of IPF and RA-ILD." (PMID 41049336, 2025). "This study investigates the potential paradoxical protective effects of this MUC5B variant in lung fibrosis." (PMID 39329706, 2024). "This investigation underscores the significance of mucin overexpression at distinct pulmonary locations, mediated by the MUC5B promoter polymorphism rs35705950, in modulating the progression of pulmonary fibrosis." (PMID 39329706, 2024). "In summary, this study reveals that mucin overexpression related to the MUC5B rs35705950 variant in the large airways significantly attenuates lung fibrosis and inflammatory responses in transgenic mice." (PMID 39329706, 2024). "It has been established so far, that expression of the MUC5B gene, responsible for mucin production in the epithelium lining of respiratory bronchioles, is the strong risk factor for pulmonary fibrosis." (PMID 39311112, 2024). "The progression of ILA changes has even been linked, in some cases, to MUC5B (mucin 5B, oligomeric mucus/gel-forming), a genetic marker linked with increasing risk for pulmonary fibrosis." (PMID 37761274, 2023). "Mutations in the genesencoding telomerase reverse transcriptase (TERT) and mucin 5B (MUC5B) are well-known genetic risk factors for pulmonary fibrosis." (PMID 36912407, 2023).
pulmonary fibrosis (continued). "A variant in the mucin 5B gene (MUC5B) is strongly associated with the risk of idiopathic pulmonary fibrosis." (PMID 37537942, 2023). "Overexpression of MUC5B in bronchoalveolar epithelium directly impairs mucociliary clearance, which plays a causative role in bleomycin-induced pulmonary fibrosis." (PMID 37063430, 2023). "It is estimated that MUC5B polymorphism (the presence of the T minor allele) increases the risk of lung fibrosis by 30–35%, thus being the most substantial single risk factor of developing IPF." (PMID 37445925, 2023). "In lung fibrosis, Nedd4-2 deficiency enhances MUC5B expression by increasing surface expression and activity of ENaC on airway epithelia cells." (PMID 35111363, 2022). "The deficiency of Nedd4-2 enhances MUC5B expression by increasing surface expression and activity of ENaC in airway epithelia cells, inducing progressive pulmonary fibrosis via impaired mucociliary clearance and dysregulation of TGF-β signaling." (PMID 35111363, 2022). "To better understand the role of cell signaling involved in MUC5B-variant-driven pulmonary fibrosis, we used publicly available single-cell and single nuclear RNA sequencing datasets (“Vanderbilt”, GEO accession GSE135893 and “Colorado”, GSE161685)." (PMID 36291184, 2022). "A series of elegant in vivo work has demonstrated that overexpression of MUC5B, both in proximal and distal airways, aggravates bleomycin-induced lung fibrosis in mice, while MUC5B-deficient mice are protected from the development of lung fibrosis." (PMID 35326501, 2022). "Seibold M.A., Wise A., Speer M., Steele M., Brown K., Lloyd J.E., FingerlinT.E., Garantziotis S., Herron A., Slifer S.H., Schwartaz D.A.A common MUC5B promoter polymorphism and pulmonary fibrosis.N." (PMID 35795226, 2022). "Of particular prominence is a strong association of a gain-of-function MUC5B gene promoter variant (rs35705950) with pulmonary fibrosis." (PMID 35479093, 2022). "Another theory for the occurrence of pulmonary fibrosis linked to MUC5B overexpression is sustained by a decrease in the lung clearance and an increased mucus viscosity." (PMID 36672608, 2022). "Although association between genetic variants and disease is not the same as causation, this finding suggests a specific role for the MUC5B promoter polymorphism and its associated increased mucin5b production in pulmonary fibrosis." (PMID 35651878, 2022). "In the BLM-induced pulmonary fibrosis mouse model, high concentration of MUC5B in airways causes mucociliary dysfunction and enhances the severity of pulmonary fibrosis." (PMID 35111363, 2022). "Lee M.G., Lee Y.H. A meta-analysis examining the association betweenthe MUC5B rs35705950 T/G polymorphism and susceptibility toidiopathic pulmonary fibrosis." (PMID 35795226, 2022). "A polymorphism in the promoter of MUC5B is strongly associated with risk of developing pulmonary fibrosis, and MUC5B overexpression enhanced pulmonary fibrosis in a mouse model." (PMID 36860703, 2022). "On the other hand, the presence of the T allele of rs35705950 (MUC5B) in patients with pre-existing idiopathic pulmonary fibrosis (IPF) seems to confer significant protection against severe COVID-19 (OR = 0.78, 95% CI 0.66–0.90)." (PMID 35892712, 2022). "The presence of MUC5B (Mucin 5B) single nucleotide polymorphisms and peripheral blood leukocyte telomere length dysfunction seems to induce pulmonary fibrosis in HP patients." (PMID 35431638, 2022). "The MUC5B gene promoter variant rs5705950 was linked to an increased susceptibility to pulmonary fibrosis in RA patients." (PMID 35479093, 2022). "Although MUC5B promoter variant (rs35705950) has been associated to an increased risk of developing pulmonary fibrosis, its role in predicting survival is contradictory." (PMID 34200784, 2021). "The G/T transversion rs35705950, located approximately 3 kb upstream of the MUC5B start site, is the cardinal risk factor for idiopathic pulmonary fibrosis (IPF)." (PMID 33320836, 2021).
pulmonary fibrosis (continued). "Subsequent studies showed that the MUC5B T-allele not only predisposes to IPF but to a variety of chronic progressive forms of pulmonary fibrosis." (PMID 34888316, 2021). "The most significant association was observed between rs35705950 (MUC5B) and idiopathic fibrosing alveolitis (OR = 2.83 [2.76 – 2.90]; P = 4.12 × 10−191), also known as idiopathic pulmonary fibrosis (IPF)." (PMID 34642702, 2021). "Genetic variants of TOLLIP and MUC5B, both on chromosome 11, have been reported to be associated with the development and/or prognosis of idiopathic pulmonary fibrosis (IPF)." (PMID 33639995, 2021). "On the other hand, excessive MUC5B is also a risk factor for developing pulmonary fibrosis, and Muc5b has a gene dosage effect on lung fibrosis in mice." (PMID 33431872, 2021). "This MUC5B variant can potentially be used to identify individuals with preclinical pulmonary fibrosis and is predictive of radiologic progression of disease." (PMID 33101356, 2020). "When we interrogated the function of these genes further, we found that many of them (e.g., MMP7, GDF15, and MUC5B) have been implicated in the pathogenesis of pulmonary fibrosis." (PMID 33082228, 2020). "The positive genetic relationship between MUC5B rs35705950 and high susceptibility to idiopathic pulmonary fibrosis is consistent with the results of previous meta-analyses and GWAS evidence." (PMID 32252656, 2020). "We found one meta-analysis published in 2013 and two meta-analyses published in 2015 regarding the association between MUC5B rs35705950 and the risk of idiopathic pulmonary fibrosis." (PMID 32252656, 2020). "Our pooling data suggest that MUC5B rs35705950 is closely associated with an increased risk of pneumonia diseases, especially idiopathic pulmonary fibrosis, in both Asians and Caucasians." (PMID 32252656, 2020). "In contrast, FOXA2 positively regulates MUC5B expression in both idiopathic pulmonary fibrosis and asthma, most likely caused by polymorphism in the MUC5B promoter." (PMID 32269574, 2020). "Both complement system and MUC5B are implicated in host defense and this MUC5B variant is associated with higher C3 gene expression in lung tissue further indicating role of complement system in pulmonary fibrosis progression." (PMID 32385381, 2020). "MUC5B rs35705950 (G/T) is strongly associated with idiopathic pulmonary fibrosis (IPF) and also contributes to the risk of interstitial lung disease (ILD) in rheumatoid arthritis (RA-ILD) and chronic hypersensitivity pneumonitis (CHP)." (PMID 31996780, 2020). "MUC5B (mucin 5, subtype B, tracheobronchial), encodes a member of the mucin family of proteins, and is associated with idiopathic pulmonary fibrosis in humans." (PMID 33488611, 2020). "MUC5B deficiency causes organisms to accumulate in upper and lower airways and is responsible for development of idiopathic pulmonary fibrosis." (PMID 33101356, 2020). "Overexpression of the MUC5B protein is associated with idiopathic pulmonary fibrosis (IPF), but little information is available regarding the pathogenic effects and regulatory mechanisms of overexpressed MUC5B in IPF." (PMID 31309122, 2019). "In a study of idiopathic pulmonary fibrosis, we reverse a paradoxical association of the strong susceptibility gene MUC5B with increased survival, suggesting instead a significant association with decreased survival." (PMID 30952951, 2019). "An SNP, rs35705950, is a G to T transversion that occurs in an area of the MUC5B 5'flanking region, 3 kb upstream of the transcription start site, exhibited the strongest association with both familial interstitial pneumonia and idiopathic pulmonary fibrosis." (PMID 31309122, 2019). "A recent GWAS meta-analysis of idiopathic pulmonary fibrosis (IPF) confirmed the strong association of mucin 5B (MUC5B) with incidence." (PMID 30952951, 2019).
pulmonary fibrosis (continued). "The identification of MUC5B as a common risk factor has altered our view of the pathogenesis of pulmonary fibrosis from alveolar epithelial cell injury and matrix deposition to mucus overproduction in the distal airways." (PMID 31309122, 2019). "Mucin 5B, oligomeric mucus/gelforming (MUC5B) has been reported as a susceptibility gene for pulmonary fibrosis." (PMID 30333048, 2018). "The gain-of-function MUC5B promoter variant rs35705950 is the dominant risk factor for developing idiopathic pulmonary fibrosis (IPF)." (PMID 30560893, 2018). "Our findings show a causative, dose-dependent role for Muc5b in murine lung fibrosis, and thus support development of mucolytic intervention strategies for human disease." (PMID 30560893, 2018). "Here the authors show that mice overexpressing Muc5b in distal airspaces show impaired mucociliary clearance and increased susceptibility to bleomycin-induced lung fibrosis, and that both characteristics are reduced by treatment with a mucolytic agent." (PMID 30560893, 2018). "MUC5B polymorphism is associated with pulmonary fibrosis, and presumably, mucin 5B is overexpressed in IPF lung tissue." (PMID 30445777, 2018). "The promoter variant rs35705950 confers a gain of function to the MUC5B gene and is the dominant risk factor for idiopathic pulmonary fibrosis." (PMID 30560893, 2018). "Collectively, these mouse lines allowed for robust gain-of-function and loss-of-function analyses of the effects of Muc5b production, and its effect in mouse models of pulmonary fibrosis." (PMID 30560893, 2018). "A recent meta-analysis that included Asian populations showed a strong association between MUC5B (rs35705950 polymorphism) and risk of idiopathic pulmonary fibrosis." (PMID 28346466, 2017). "The variation of G>T in the MUC5B promoter (rs35705950) has been associated with idiopathic pulmonary fibrosis (IPF) and familial interstitial pneumonia (FIP) in Caucasians, but no information is available regarding this variant in the Chinese population." (PMID 25121989, 2014). "The strong association of the MUC5B variant with idiopathic pulmonary fibrosis was recently confirmed in other European Caucasian populations, including Italian, French, and British cohorts, and confirmed in two genome-wide association studies." (PMID 25121989, 2014). "A polymorphism (rs35705950) in the promoter region of the mucin MUC5B is associated with both familial and sporadic forms of idiopathic pulmonary fibrosis." (PMID 24667072, 2014). "Recently, a common variant in the promoter region of the mucin 5B (MUC5B) gene was found to be associated with the development of idiopathic pulmonary fibrosis as well an increased production of MUC5B, an airway mucin." (PMID 24667072, 2014). "Emerging efforts to evaluate the role of the susceptibility loci for pulmonary fibrosis have led to unexpected results, as demonstrated by the discovery of the association of MUC5B variant with disease risk, but improved disease prognosis." (PMID 24391588, 2013). "The rs35705950 risk Single Nucleotide Polymorphism (SNP) for pulmonary fibrosis in the MUC5B region has generated a lot of interest." (PMID 24391588, 2013). "We previously identified a MUC5B gene promoter-variant that is a risk allele for sporadic and familial Idiopathic Pulmonary Fibrosis/Usual Interstitial Pneumonia (IPF/UIP)." (PMID 23527003, 2013). "The implication of genetic polymorphisms in SFTPA2, SFTPC, MUC5B as well as DSP (encoding desmoplakin) as risk factors for pulmonary fibrosis suggest that the integrity of the barrier function is critically important in maintaining lung homeostasis." (PMID 24391588, 2013). "Interestingly, a MUC5B promoter variant rs35705950 is the strongest genetic risk factor for idiopathic pulmonary fibrosis." (PMID 41541775, 2026). "The MUC5B promoter variant results in spatial proteomic changes that may be associated with initiaiton and progression of lung fibrosis." (PMID 40526433, 2025).